SLC7A11 (solute carrier family 7 member 11)
Diseases named in the same sentence as SLC7A11 in open-access papers (continued):
Sharing a sentence is not in itself a finding about the gene and the disease.
cancer (continued). "Taken together, these studies suggest that SLC7A11 overexpression induces both glutamine and glucose dependency in cancer cells with different underlying mechanisms." (PMID 33000412, 2021). "SLC7A11 has also been associated with cell death regulated by reactive oxygen species in human cancers." (PMID 33152221, 2021). "Our results revealed SLC7A11 is implicated in the overall survival of several cancers, including ACC, BLCA, HNSC, KICH, KIRC, LGG, LIHC, and SKCM." (PMID 34938318, 2021). "Overexpression of SLC7A11 was identified as a risk factor for worse OS in eight cancers (ACC, BLCA, HNSC, KICH, KIRC, LGG, LIHC, and SKCM) (HR > 1, p < 0.05)." (PMID 34938318, 2021). "Specifically, 25/27 (92.6%) cancers were featured with upregulated SLC7A11 expression, where SLC7A11 overexpression is a risk factor for worse overall survival in 8 cancers." (PMID 34938318, 2021). "The stacked evidence demonstrated that SLC7A11 is upregulated in many cancers and is associated with drug resistance and patients’ poor prognosis." (PMID 37287758, 2021). "SLC7A11 expression is lower in ARID1A-deficient compared with ARID1A-proficient cancer cells, contributing to a decrease in basal GSH levels and an increase in ROS in ARID1A-deficient cells." (PMID 32978257, 2020). "Many cancer cell lines highly express the Na+-independent cystine/glutamate antiporter xCT, which is encoded by the SLC7A11 gene." (PMID 31100816, 2019). "Specifically, it has been shown that deficiency of ATF4 or NRF2 expression decreases SLC7A11 expression, and similar to SLC7A11 deficiency, improves cancer cell survival under glucose starvation." (PMID 29764521, 2018). "SXC-2023, in particular, has shown potential in modulating various cellular pathways, and its effects on SLC7A11 could increase the susceptibility of cancer cells to ferroptosis, which may lead to better treatment outcomes." (PMID 41561226, 2026). "However, during glucose starvation conditions SLC7A11‐high cancer cells exhibit actin cytoskeleton‐associated disulphidptosis resulting from NADPH depletion‐induced disulphide stress." (PMID 39354653, 2025). "Additionally, the dysregulation of SLC7A11 has been linked to several pathological conditions, including neurodegenerative diseases and cancer, underscoring its importance in cellular metabolism and survival." (PMID 40535572, 2025). "However, in a variety of cancer lines, JQ-1 has been reported to promote erastin-induced ferroptosis by downregulating a number of genes associated with this process, such as SLC7A11, SLC3A2, and GPX4." (PMID 40695797, 2025). "SLC7A11 mutations in multiple types of cancers were screened in the cBioPortal database." (PMID 40978058, 2025). "While SLC7A11 is up-regulated in diverse tumors which predicts adverse outcomes of patients, the underlying mechanisms by which cancer cells adapt to increased SLC7A11 levels remain largely unknown." (PMID 38959043, 2024). "Furthermore, numerous studies have confirmed that SLC7A11 is overexpressed in a variety of cancers and is associated with poor patient prognosis." (PMID 39029955, 2024).
cancer (continued). "Moreover, Mahmood Hassan Dalhat demonstrates that in NAT10-depleted cancer cells, the expression of essential genes such as SLC7A11, which are associated with ferroptosis, are significantly downregulated." (PMID 39251905, 2024). "Additionally, our study comprehensively explored the pan-cancer expression profiles, prognostic significance, and associations with immune checkpoints of SLC7A11." (PMID 38655266, 2024). "Notably, the overexpression of SLC7A11 leads to heightened consumption of glutamine for glutathione synthesis, a hallmark of glutamine addiction in cancer cells." (PMID 38655266, 2024). "Additionally, SLC7A11 is overexpressed in many different cancer types and is associated with a poor prognosis for patients." (PMID 38968580, 2024). "Moreover, BAP1 mutants associated with cancer were found to lose their ability to repress SLC7A11 and to promote ferroptosis." (PMID 38267442, 2024). "Additionally, pan-cancer analyses indicated an association between SLC7A11 and the expression of immune checkpoint genes across multiple cancer types with poor prognoses." (PMID 38655266, 2024). "Also, overexpression of SLC7A11 in PDAC-derived cancer-associated fibroblasts (CAFs) was demonstrated in a study." (PMID 38705513, 2024). "Furthermore, SLC7A11 is implicated in ferroptosis, a novel cell death mechanism, and its expression is regulated by malignant tumor therapies, such as immunotherapy and radiation therapy." (PMID 39350768, 2024). "However, the emerging susceptibility of these cancer cells to disulfidptosis introduces a new avenue for therapeutic intervention in SLC7A11-high malignancies." (PMID 38428031, 2024). "Interestingly, the authors found that the vulnerability of ARID1A-deficient cancer cells is caused by low basal GSH levels due to a decreased expression of SLC7A11." (PMID 38203758, 2024). "Additionally, the administration of NAC and 2-ME markedly prevented the cell death induced by APR-246, suggesting that the loss of SLC7A11 exacerbates oxidative stress in cancer cells." (PMID 39532848, 2024). "Furthermore, elevated expression of SLC7A11 has been linked to increased aggressiveness and drug resistance in various types of cancers." (PMID 39600313, 2024). "Moreover, the SLC7A11-high cancer cells are particularly susceptible to disulfidptosis under glucose starvation conditions; however, these cells are more likely resistant to apoptosis- and ferroptosis-inducing therapies." (PMID 38671348, 2024). "Notably, evidence suggests that SLC7A11 is a key oncogenic protein that influences malignant cancer behavior, tumor microenvironment, immune system, cancer-associated syndromes, and therapeutic susceptibility." (PMID 38968580, 2024). "Consequently, SLC7A11 inhibitors cause excessive lipid peroxidation and ferroptosis in various cancer cells." (PMID 39624080, 2024). "In addition, significant correlations between SLC7A11 and a variety of cancer-infiltrating immune cells were reported, showing potential causality of SLC7A11 in regulation of T cell function in LUAD." (PMID 37315289, 2023). "We propose that this may be due to the excessive susceptibility of SLC7A11-high cancer cells to cell death induced by oxidative stress during metastasis." (PMID 37339981, 2023). "Elevated SLC7A11 expression has been linked to apoptosis in glucose-starved cancer cells." (PMID 37892851, 2023). "It has been revealed that in glucose-deficient SLC7A11-high cancer cells, a large accumulation of disulfide molecules leads to abnormal disulfide bonding between actin cytoskeletal proteins, disrupting their organization and eventually leading to actin network collapse and cell death." (PMID 37759294, 2023). "The association between SLC7A11 and clinicopathological features in cancers." (PMID 36874967, 2023).
cancer (continued). "Moreover, SLC7A11 is a suppressor of ferroptosis, and its overexpression is associated with a poor prognosis in various cancers." (PMID 36605944, 2022). "In addition, the modulation of SLC7A11 overexpressed in many types of cancers and is associated with patients’ poor prognosis." (PMID 35309947, 2022). "Considering the frequent mutations of SLC7A11 in several types of cancer, triggering ferroptosis for cancer therapy may be a promising approach." (PMID 35531466, 2022). "CD44 variant (CD44v) isoforms interact with and stabilize SLC7A11 in cancer cells." (PMID 35280777, 2022). "High SLC7A11 levels prime cellular cystine influx, maintaining glutathione levels and preventing ferroptotic cell death, which in turn poses a risk for resistance to cancer therapies, including in PC (as reviewed)." (PMID 36010941, 2022). "Finally, since SLC7A11 has been linked to cancer through multiple approaches, we propose that its contribution and regulatory mechanism require further elucidation." (PMID 35804831, 2022). "Additionally, BAP1 deficiency in cancer cells is associated with SLC7A11 upregulation and ferroptosis resistance." (PMID 35280777, 2022). "Therefore, inhibition of SLC7A11 together with the inhibition of TXNRD1 predisposes cancer cells to “disulfide stress”, and further induces cell death." (PMID 35453395, 2022). "SLC7A11 also has potential roles in cancer-associated fibroblasts or vascular remodelling." (PMID 35804831, 2022). "Additionally, SLC7A11 has a potential role in cancer-associated fibroblasts (CAFs) or vascular remodeling." (PMID 36552652, 2022). "A high expression level of SLC7A11 was associated with altered cell metabolism, characterised by increased mitochondrial biogenesis, oxidative phosphorylation or ATP production, leading to increased resistance to cisplatin in cancers." (PMID 36485069, 2022). "Various diseases, including cancer, have been linked to abnormal ferroptosis, and inhibition of SLC7A11 and GPX4 may eradicate cancer cell resistant to chemotherapy, targeted therapy or radiotherapy." (PMID 35402284, 2022). "For example, ARID1A (AT-rich interaction domain 1A)-deficient cancer cells, of which enhanced SLC7A11 expression by ARID1A-mediated chromatin remodeling disappears, are more susceptible to inhibition of the antioxidant glutathione due to excessive amounts of ROS-triggered apoptosis." (PMID 35178349, 2022). "In addition to ferroptosis, SLC7A11 inhibition has been linked to apoptosis in murine melanocytes and cancer cells in a context dependent manner." (PMID 35280777, 2022). "Here, we conducted a bioinformatic study to systematically explore whether the intra-tumoral expression of SLC7A11 is associated with cancer patients’ prognosis and response to immunotherapy." (PMID 34938318, 2021). "Except for these cancers, SLC7A11 is associated with the DSS for PARD and KIRP." (PMID 34938318, 2021). "Additionally, growing evidence has demonstrated that SLC7A11 is overexpressed in various types of cancers and is associated with patients' poor prognosis." (PMID 34446045, 2021).
cancer (continued). "MiR-489-3p/SLC7A11 axis may just one of the downstream mechanisms underlying levobupivacaine-induced ferroptosis and anti-cancer activities and more related studies are needed to perform in the future." (PMID 34177591, 2021). "In addition, the association between immune score and SLC7A11 expression is dependent on cancer type." (PMID 34938318, 2021). "Conversely, in cancers which carry CCDC6 mutated forms, or that have lost CCDC6 expression, cancer cells may lose their abilities to repress xCT/SLC7A11 and to promote ferroptosis." (PMID 34841108, 2021). "Therefore, SLC7A11 likely represents a better therapeutic target for cancer treatment than GPX4 because inhibiting SLC7A11 would presumably cause less toxicity in patients than inhibiting GPX4." (PMID 34162423, 2021). "MiR-382-5p/SLC7A11 axis may be just one of the downstream mechanisms underlying lidocaine-repressed cancer progression and more mechanisms are needed to be explored in future investigation." (PMID 34122108, 2021). "Given that SLC7A11 was associated with the prognoses in multiple cancers, we studied whether SLC7A11 affected the proliferation of cancer cells." (PMID 34938318, 2021). "In addition to its well-recognized role in orchestrating antitumor immune responses, prior experimental evidence indicates that IFNG can modulate ferroptotic susceptibility by downregulating SLC7A11 expression and enhancing lipid peroxidation in select cancer contexts." (PMID 40868287, 2025). "Notably, the overexpression of SLC7A11 has been associated with unfavorable outcomes in various cancers, suggesting that it may serve as a promising therapeutic target." (PMID 40535572, 2025). "However, cystine starvation could rescue glucose starvation-induced cell death in SLC7A11high cancer cells and render such cells less susceptible to ferroptosis induced by SLC7A11 inhibition." (PMID 36552652, 2022). "Therefore, targeting metabolic vulnerabilities associated with SLC7A11 may prove to be a better therapeutic strategy against cancer." (PMID 35280777, 2022). "Thus far, SLC7A11 targeting strategies include either directly inhibiting SLC7A11 transporter activity or indirectly targeting SLC7A11-associated metabolic susceptibilities and pathways in cancer." (PMID 35280777, 2022). "Therefore, it is critical to determine whether their anti-cancer effect under any given context is indeed caused by SLC7A11 inhibition and ferroptosis induction." (PMID 33000412, 2021). "Hence, we elaborated a bioinformatic study in pan-cancer level to systematically explore whether the intra-tumoral expression of SLC7A11 is associated with patients’ survival and its potential value in immunotherapy." (PMID 34938318, 2021). "However, the association of SLC7A11 with cancer drug resistance remains poor." (PMID 34790572, 2021). "Moreover, cancer-associated BAP1 mutants lose its inhibition of SLC7A11 and repress ferroptosis." (PMID 33294126, 2020). "Another recent study also uncovered a similar role of SLC7A11 in regulating glutamine dependency from a very different perspective by identifying environmental factors that cause differential dependencies on glutamine in cancer cells cultured in different media." (PMID 29764521, 2018). "Kirsten rat sarcoma virus oncogene homolog (KRAS)-mutant cancer cells increase transferrin receptor 1 and SLC7A11 expression, highlighting the link between KRAS mutation and ferroptosis." (PMID 41596341, 2026). "Mechanistically, treatment downregulated key nucleotide biosynthesis genes (DHFR, TK1) and the glycolytic enzyme gene (ENO1), while upregulating the oxidative stress response gene SLC7A11 (18.32-fold), suggesting disruption of cancer metabolic pathways." (PMID 42074264, 2026).
cancer (continued). "Mechanistically, NRF2 promotes cystine uptake by driving SLC7A11 expression, which increases intracellular cysteine levels to promote these cysteine fates in a panel of cancer cell lines." (PMID 41946999, 2026). "Samples from each cancer type were stratified into four groups based on the gene expression levels of SLC7A11 and the protein expression level of α-actin." (PMID 41346703, 2026). "In summary, our results demonstrated that HED synergistically promoted the anti-cancer effects of SOR on HCC cells by suppressing SLC7A11 expression, thereby triggering ferroptosis." (PMID 42254442, 2026). "Previous studies have reported that the disulfidptosis-related gene SLC7A11 regulates expression in most cancers and mediates multiple regulatory mechanisms." (PMID 39926285, 2025). "The crosstalk between disulfidptosis and ferroptosis, particularly involving the SLC7A11 and cystine system, has also been further elucidated in cancers." (PMID 40900810, 2025). "Cancer cells heavily rely on the SLC7A11 system to facilitate the transportation of cystine from the extracellular environment into the cell." (PMID 40535804, 2025). "Previous studies have demonstrated that SLC7A11‐high cancer cells exhibit a strong reliance on glucose and undergo rapid cell death when deprived of glucose." (PMID 39354653, 2025). "Most cancer cells primarily obtain cysteine by uptake of extracellular cysteine (an oxidized cysteine dimer) through the solute carrier family 7 member 11 (SLC7A11)." (PMID 39987145, 2025). "Cancer cells obtain cystine from the environment via the cystine/glutamate antiporter SLC7A11 (xCT), which exchanges extracellular cystine for intracellular glutamate." (PMID 40259435, 2025). "Overexpression of SLC7A11 is commonly observed in cancer cells, where it facilitates cystine uptake, thereby protecting these cells from oxidative stress and ROS‐mediated cell death, including ferroptosis." (PMID 40900810, 2025). "Most cancer cells absorb extracellular cystine primarily through the cystine transporter (comprising the catalytic subunit SLC7A11 and the chaperone subunit SLC3A2); cystine is reduced to cysteine for cell utilization." (PMID 41438431, 2025). "SLC7A11 plays a pivotal role in the inhibition of ferroptosis, and its overexpression confers a survival advantage to cancer cells." (PMID 39354653, 2025). "Decreasing the expression levels of SLC7A11 reduced the proliferation of MDA-MB-231 cells, and conversely, the addition of GluOC interfered with the inhibition of si SLC7A11 on cancer cells." (PMID 40075587, 2025). "Given the pivotal role of SLC7A11 in cancer development and its function as a “trigger” in multiple forms of regulated cell death, SLC7A11—located on human chromosome 4—was selected as the primary focus of this study." (PMID 41330917, 2025). "High levels of SLC7A11 expression are found in human malignancies, which prevent cancer cells from undergoing ferroptosis." (PMID 40916076, 2025). "For instance, the deubiquitinating enzyme OTUB1 directly interacts with SLC7A11 to inhibit its ubiquitination, thereby stabilizing SLC7A11 and suppressing ferroptosis in cancer cells." (PMID 40825027, 2025). "Cancer cells predominantly obtain intracellular cysteine via solute carrier family 7 member 11 (SLC7A11 or xCT), the transporter component of the system Xc−." (PMID 40821110, 2025). "SLC7A11 (xCT) enables cystine uptake for glutathione synthesis, protecting cancer cells from oxidative stress and ferroptosis." (PMID 41154605, 2025). "Cellular disulfide stress, characterized by NADPH depletion and abnormal accumulation of disulfide molecules, is a critical event in SLC7A11-high cancer cells." (PMID 40012016, 2025). "In this review, we present recent progress in understanding ferroptosis induction and defense systems and summarize the latest advancements in SLC7A11 research, including its structure, regulation, expression profiles, and prognosis in cancer patients." (PMID 39569390, 2025).